SNHG6 (small nucleolar RNA host gene 6)
Diseases named in the same sentence as SNHG6 in open-access papers (continued):
Sharing a sentence is not in itself a finding about the gene and the disease.
tumor (continued). "Besides, SNHG6 may interfere with anti-tumor immune responses by affecting macrophages and cancer-associated fibroblasts in the tumor microenvironment, and may also promote KIRP progression by regulating the expression of molecules such as EZH2." (PMID 37004005, 2023). "Also, the SNHG6 expression level was studied in different grades of tumor samples." (PMID 35096086, 2022). "In addition, miR-944 plays a tumor-suppressive role in PA, and SNHG6 can negatively regulate it." (PMID 32935999, 2022). "Furthermore, SNHG6 knockdown repressed GC tumor growth in vivo." (PMID 34821362, 2021). "Our studies suggested that SNHG6 might act as a tumor promoting factor in NSCLC." (PMID 32147945, 2020). "Furthermore, SNHG6 knockdown improved 5-FU therapy and resulted in a higher tumor growth inhibition rate, which indicates that SNHG6 might enhance 5-FU resistance in CRC cells in vivo." (PMID 31516391, 2019). "Translational regulation and signaling pathway activation: SNHG6 interacts with the RNA-binding protein YBX1 to enhance the translation of HIF1α, promoting tumor growth and metastasis in ccRCC." (PMID 41301542, 2025). "So far, several lipid‐associated lncRNAs, including small nucleolar RNA host gene 3 (SNHG3), small nucleolar RNA host gene 6 (SNHG6), and LINK‐A (formerly LINC01139), have been found to be involved in tumor progression." (PMID 40111100, 2025). "Using TCGA, GTEx, UALCAN, TIMER, TIMER 2.0 and STRING databases, we analyzed the relationship of SNHG6 with KIRP subtypes, tumor-infiltrating immune cells and potential target mRNAs." (PMID 37004005, 2023). "Consistent with our study, SNHG6 serves as a tumor suppressor, and ZEB1-AS1 acts as a tumor promoter." (PMID 36275644, 2022). "SNHG6 and MALAT1 also demonstrated differential expression between normal tissues and tumor tissues." (PMID 35627262, 2022). "Overexpression of SNHG6 represses miR-181a, which in turn induces JAK2 expression and promotes tumor cell proliferation." (PMID 35740344, 2022). "For example, tumor-killing immune cells in the high expression group of SNHG16, SNHG6, SNHG11, FAM222A-AS1, RHPN1-AS1, SNHG1, and SNHG7 were significantly lower than those in the low." (PMID 35646635, 2022). "Compared with that in normal tissues and cells, small nucleolar RNA host gene 6 (SNHG6) and RSF1 expression are upregulated, while miR-490-3p expression is downregulated, in NSCLC tumours and cell lines." (PMID 34147108, 2021). "SNHG6 upregulation, measured by qRT-PCR, improves the proliferation, invasion, migration, viability, and EMT rate of tumor cells." (PMID 34885097, 2021). "In summary, these data elucidated that SNHG6 was regulated by SP1 on the transcriptional level and was involved in the tumor-promoting effect of SP1." (PMID 33431838, 2021). "Simultaneously, we found that patients with high levels of SNHG6 in cancer tissues had a tendency to develop advanced TNM stage, earlier distant metastasis, positive lymph node metastasis, and deeper tumor invasion." (PMID 32000704, 2020). "Generally, SNHG6 was found to be upregulated in CRC tissues and cell lines and responsible for high tumor grades and poor patient survival." (PMID 32518528, 2020). "Thus, we speculated that EZH2 might be involved in tumor-promoting functions of SNHG6." (PMID 30626446, 2019). "Further functional experiments demonstrated that knockdown of SNHG6 in OCCC cells inhibited cell proliferation, migration and invasion in vitro as well as tumour growth in vivo." (PMID 31119871, 2019). "To support this conclusion, we detected SNHG6 expression from 55 clinical CRC patient samples by qRT- PCR assays, which was ubiquitously increased compared to adjacent non-tumor tissues (P < 0.001)." (PMID 31533634, 2019). "In this study, we revealed that SNHG6 was overexpressed in OCCC tissues and that this lncRNA promoted cell proliferation, migration and invasion in vitro as well as tumour growth in vivo." (PMID 31119871, 2019).
tumor (continued). "SNHG6 was expressed at the tumor edge and in the pseudopalisading regions around necrosis, but most lncRNAs (Pvt1, SNHG12, H19, Neat1, Malat1, Mir17hg and Ftx) were expressed around the necrotic tumor regions." (PMID 40527978, 2025). "In prostate cancer, SNHG6 modulates cancer cell sensitivity to paclitaxel by sponging miR-186, SNHG12 influences tumorigenesis through targeting miR-133b, and SNHG4 enhances ZIC5-mediated tumor growth and metastasis via the regulation of miR-377." (PMID 41301542, 2025). "We found that SNHG6 KD attenuated tumor cell proliferation both in vitro and in vivo, but did not affect the response to a bona fide cytotoxic agent." (PMID 38419051, 2024). "Similarly binding to miR-26b-5p affects the Hedgehog signaling pathway, and miR-15a sponging by SNHG6 has been seen to affect TAK1/JNK and Wnt/β-catenin signal pathways promoting cancer cell growth, invasion, migration, EMT and represses tumor apoptosis." (PMID 37735423, 2023). "In this research, we focused on the SNHG6 expression pattern of CRC tumors and non-tumor tissues." (PMID 35096086, 2022). "Some of these 32 tumor tissues had no detectable SNHG6 expression; thus, they were excluded from statistical analyses." (PMID 35096086, 2022). "The low expression group of SNHG16, SNHG6, SNHG11, FAM222A-AS1, RHPN1-AS1, SNHG1, and SNHG7 was accompanied by more immune cell infiltration, further supporting that PANoptosis plays a crucial role in the tumor immune microenvironment." (PMID 35646635, 2022). "Mechanistic study revealed that SNHG6 could recruit EZH2 and maintain high level of H3K27me3 to repress the transcription of tumor-suppressor genes, including KLF6." (PMID 33431838, 2021). "Taken together, our data here proved that SNHG6 could directly interact with EZH2 and repress the expression of tumor-suppressor genes through H3K27me3 histone methylation." (PMID 33431838, 2021). "Given all the confounding factors, multivariate Cox regression analysis unveiled that high expression of SNHG6 was an independent prognostic factor of tumor recurrence rather than poor survival in LAC patients." (PMID 32147945, 2020). "Mechanistically, SNHG6 was identified to abolish miRNA-induced repression of ZEB1 by binding miR-101-3p and inducing epithelial-mesenchymal transition (EMT), thus modulating tumor growth and metastasis." (PMID 32000704, 2020). "High lncRNA SNHG6 expression was correlated with tumor invasion depth, LNM, DM, and advanced TNM stage, suggesting that SNHG6 may serve as a promising prognostic biomarker of human cancers." (PMID 32321469, 2020). "Recently, small nucleolar RNA host gene 6 (SNHG6), linc00152, and opa-interacting protein 5 antisense RNA 1(OIP5-AS1) have been identified as potential prognostic biomarkers involved in the modulation of tumour-related genes and specific molecular mechanisms in human cancers." (PMID 33243205, 2020). "However, they did not uncover how SNHG6 exerted its tumor-promoting effects." (PMID 30626446, 2019). "Consistently, the clinical correlation between the expression of EZH2, KLF-6, Sp-1, and SNHG6 in patient tumor samples also showed that both EZH2 and Sp-1 displayed the positive correlation with SNHG6, whereas KLF6 and p21 exhibited the negative correlation with SNHG6." (PMID 33431838, 2021).
cancer (50 papers, 2017 to 2025). A tumor composed of atypical neoplastic, often pleomorphic cells that invade other tissues. "SNHG6 overexpression results in increased cancer survival and metastasis so it can be used as a diagnostic as well as a prognostic marker." (PMID 37735423, 2023). "In the immune microenvironment of KIRP, SNHG6 expression levels were negatively correlated with macrophage abundance and positively correlated with cancer-associated fibroblasts." (PMID 37004005, 2023). "In vivo and in vitro Loss of function studies provided evidence that SNHG6 knockdown not only inhibits cancer cell metastasis but also its proliferation." (PMID 37735423, 2023). "Small nucleolar RNA host gene 6 (SNHG6) is deemed as a promising prognostic biomarker of many human cancers and has close association with several clinicopathological characteristics." (PMID 34821362, 2021). "Up till now, the underlying molecular mechanisms involved in SNHG6 interactions in cancers are complex and remain poorly understood." (PMID 32321469, 2020). "Five studies were finally included in this meta-analysis aimed to evaluate the association between SNHG6 expression and OS of cancer patients." (PMID 32655318, 2020). "In summary, the results of this meta-analysis support that SNHG6 overexpression is significantly associated with a poor prognosis in human cancers." (PMID 32655318, 2020). "The results demonstrated that a high expression of SNHG6 was significantly associated with an increased risk of poor overall survival (OS) in cancer patients (HR = 2.06, 95% CI 1.56–2.73)." (PMID 32655318, 2020). "The purpose of the present meta-analysis was to comprehensively elucidate the association between SNHG6 expression and clinical outcomes in cancers." (PMID 32321469, 2020). "The violin plot indicated that SNHG6 expression was significantly associated with clinical stage in these human cancers." (PMID 32655318, 2020). "Notably, MEG3, MIAT, Malat1, SNHG20, SNHG12, Ftx, Pvt1, Mir9-3hg expression in cancer immune cells was associated with an immunosuppressive phenotype, while H19, SNHG6, Trp53cor1, MiR17hg and MiR142hg were linked to a pro-inflammatory phenotype in cancer." (PMID 40527978, 2025). "Additionally, we conducted a meta-analysis to evaluate the association between SNHG6 expression and other clinical characteristics in cancer patients." (PMID 32000704, 2020). "Overexpressed SNHG6 was significantly associated with poor prognosis in various cancers." (PMID 32655318, 2020). "The splice variants of SNHG6 could have their expression pattern in distinct cancers." (PMID 36247503, 2022). "Here we establish broad relevance of 2 snoRNA host genes, SNHG16 and SNHG6, to a variety of cancers and neuropsychiatric disorders specifically through their relationship with vitamins, well supported by multiple studies." (PMID 38475720, 2024). "SNHG6 (small nucleolar RNA host gene 6) is another lncRNA that is located in chromosome 8q13.1, thus being amplified in many cancers, including HCC." (PMID 38203767, 2024). "Experiments conducted in various cancer cell lines have shown that the oncogenic effects of SNHG6 can be reversed by artificially increasing the expression of its targeted microRNAs." (PMID 37735423, 2023). "The role of SNHG6 in cancer cell growth, metastasis, and apoptosis is indirectly regulated via its effect on the target miRNA and the following downstream pathway." (PMID 37735423, 2023). "A comprehensive literature review and analysis were undertaken to delve into the biogenesis of SNHG6, its roles in cellular processes, and the mechanisms through which it contributes to the hallmarks of cancer." (PMID 37735423, 2023). "Small nucleolar RNA host gene 6 (SNHG6), a lncRNA located in chromosome 8q13.1, has been shown to be linked to poor outcomes in a variety of human cancers." (PMID 37004005, 2023). "SNHG6 downregulates p21 and KLF2 while enhancing cyclin D1 activity causing cancer cell proliferation and inhibiting apoptosis." (PMID 37735423, 2023).
cancer (continued). "This study provided evidence of SNHG6 involvement in metabolism alteration and ultimately cancer development." (PMID 37735423, 2023). "Researchers found that SNHG6 is highly expressed in various cancer types, particularly in HCC, and its high expression is linked to disease progression and poor patient outcomes." (PMID 37735423, 2023). "By suppressing β-catenin and E-cadherin protein expression and promoting N-cadherin and vimentin translation SNHG6 not only increases cancer cell proliferation but also promotes EMT of cancer cells." (PMID 37735423, 2023). "This review focuses on the lncRNA SNHG6, aiming to elucidate its biogenesis, the pivotal roles it plays, and its mechanisms in facilitating the hallmarks of cancer." (PMID 37735423, 2023). "EZH2 is considered to be a new target for cancer therapy and has been shown to be a downstream target gene regulated by SNHG6 in a variety of malignancies." (PMID 37004005, 2023). "Research has demonstrated the role of SNHG6 as a competing endogenous RNA (ceRNA) in multiple types of cancer." (PMID 37735423, 2023). "SNHG6 was proved as an oncogenic RNA and is involved in cancer progression, such as breast, brain, prostate, or lung cancers." (PMID 36247503, 2022). "We report elevated levels of SNHG6 in tamoxifen-resistant cells, which is in agreement with the published literature about the oncogenic role of SNHG6 in human cancers." (PMID 36212408, 2022). "Further, SNHG6 silencing reduced cancer stem cell markers Sox2, Oct4 and EZH2 in T47DTR cells, relative to parental T47D cells, and anti-miR-101 oligomers significantly (p<0.01) attenuated this effect." (PMID 36212408, 2022). "Our novel information on the modulation of tamoxifen resistance by this SNHG6-miR-101 axis adds new knowledge, and should further generate interest in the evaluation of miR-101 targeting by SNHG6 in the context of cancer drug resistance." (PMID 36212408, 2022). "miR-944 can also inhibit the EMT process of cancer cells by participating in the SNHG6/miR-944/RAB11A axis." (PMID 36077769, 2022). "In pituitary adenoma (PA), the SNHG6/miR-944/RAB11A axis promotes cancer cell proliferation, invasion, migration, and EMT." (PMID 36077769, 2022). "Numerous studies have confirmed the prognostic value and clinical potential of SNHG6 in cancer, serving as a competitive endogenous RNA as one of the primary mechanisms underlying its role." (PMID 35837104, 2022). "LncRNA small nucleolar host gene 6 (SNHG6) have been proven as an oncogenic transcript in many types of cancer." (PMID 36247503, 2022). "In recent years, accumulating evidence have revealed that SNHG6 was aberrantly expressed in various cancers and was significantly correlated with clinical stage and prognosis." (PMID 34638381, 2021). "The pooled results revealed that SNHG6 expression was an independent prognostic factor for OS in cancer patients (HR = 2.21, 95% CI: 1.46–2.96, p < 0.001; I2 = 0.0%, p = 0.892)." (PMID 32321469, 2020). "Small nucleolar RNA host gene 6 (SNHG6) is a long non‐coding RNA (lncRNA) which plays a critical role in cancer progression." (PMID 32147945, 2020). "In recent years, accumulating evidence revealed that SNHG6 was aberrantly expression in various types of cancers and was significantly correlated with clinical stage and prognosis." (PMID 32655318, 2020). "Similar to its role in HCC, SNHG6 is upregulated in GC and its high expression influences cancer cell characteristics, such as cell growth, migration capacity, and EMT." (PMID 32518528, 2020). "SNHG6, as a novel cancer-related lncRNA, is located at chromosome 8q13 and has an evident connection with the structural integrity of the translation initiation complex and ribosomes, and it has become a new frontier of research." (PMID 32000704, 2020). "In the current meta-analysis, we explored the possibility of a relationship between SNHG6 expression levels and cancer prognostic parameters and pathological attributes by incorporating 14 studies." (PMID 32000704, 2020).
cancer (continued). "The pooled data also showed a relationship between SNHG6 overexpression with poor OS in human cancers (corrected HR = 2.16, 95% CI: 1.70–2.75, p < 0.001)." (PMID 32321469, 2020). "Recently, accumulating evidence has suggested that the aberrant expression of SNHG6 exists in a variety of tumors and has a correlation with poor clinical outcomes across cancer patients." (PMID 32000704, 2020). "SNHG1 contributes to cell growth and survival in several cancer types, and we also found it connected with other known cancer‐associated lncRNAs, such as GAS5 and SNHG6." (PMID 32460441, 2020). "Recent studies have reported that SNHG6 is highly expressed in variety of cancer tissues (except CCA) and overexpressed SNHG6 reduces cell apoptosis but promotes cell cycle, cell migration, invasion, EMT, and chemoresistance." (PMID 32226515, 2020). "In the future, more well-designed studies with larger sample size are needed to validate the prognostic value of SNHG6 in different cancers of various ethnic populations." (PMID 32321469, 2020). "It has been reported that SNHG6 has been found to function as an oncogene in various cancers, including CRC, hepatocellular carcinoma, and breast cancer." (PMID 32296635, 2020). "SNHG6 has been observed to exhibit increased expression in many cancer types." (PMID 37735423, 2023). "As autophagy plays important role in many physiological and pathophysiological pathways, the regulatory role of SNHG6 towards autophagy also provides it with the regulatory role in such processes that include autoimmune diseases, cancer progression, cancer inhibition, and chemoresistance." (PMID 37735423, 2023). "Furthermore, the whole mechanism of SNHG6 in regulating miRNAs in promoting cancer hallmarks is also highlighted." (PMID 37735423, 2023). "SNHG6 is one of the factors involved in altered metabolisms of cancer cells." (PMID 37735423, 2023). "In addition, SNHG6 served as a promising biomarker in the prediction of prognosis and clinicopathological features in varieties of human cancers." (PMID 36494339, 2022). "Our hypothesis to focus on SNHG6 for this study was based on the published literature supporting a role of SNHG6 in cancer drug resistance, coupled with the fact that its role specifically in tamoxifen resistance has never been elucidated." (PMID 36212408, 2022). "Thus, specific targeting of miR-101 by SNHG6 is functionally relevant not only in various cancers but in several other physiological phenomena as well." (PMID 36212408, 2022). "Raised SNHG6 expressions was intricately related to poorer overall survival in cancer patients." (PMID 34026654, 2021). "In addition, we up-regulated miR-6509-5p in Hep3B and Huh7 cells, and found the cancer progression of cells treated with miR-6509-5p mimics was slowed down, indicating SNHG6 indeed functioned as the sponge of miR-6509-5p." (PMID 33663502, 2021). "In cancer-related studies, SNHG6 has been connected with the process of EMT." (PMID 34485294, 2021). "However, due to the limitations of our study, more well-designed studies are warranted to validate the role of SNHG6 in human cancers." (PMID 32655318, 2020). "In summary, elevated SNHG6 plays a vital role in cancer cell proliferation, migration and invasion." (PMID 32655318, 2020). "SNHG6 was pointed out to play a carcinogenic role in diverse cancers." (PMID 32782439, 2020). "However, given the discrete outcomes and limited sample size in current studies, we performed this meta-analysis to evaluate the potential value of SNHG6 as a promising prognostic biomarker in human cancers." (PMID 32321469, 2020). "Therefore, this meta-analysis was conducted to investigate the potential prognostic value of SNHG6 in human cancers." (PMID 32655318, 2020). "SNHG6 expression was upregulated in the majority of malignant tumors than in normal tissues." (PMID 32226515, 2020). "Due to its oncogenic potential, lncRNA SNHG6 is defined as a carcinogenic lncRNA in many cancers." (PMID 32321469, 2020).